CYP27B1 (cytochrome P450 family 27 subfamily B member 1)
Diseases named in the same sentence as CYP27B1 in open-access papers (continued):
Sharing a sentence is not in itself a finding about the gene and the disease.
melanoma (24 papers, 2012 to 2025). A malignant, usually aggressive tumor composed of atypical, neoplastic melanocytes. "CYP27B1 expressions have been reported to be inversely correlated with the development of melanoma, and low or undetectable levels have been linked to poor prognosis." (PMID 38672780, 2024). "Low expression of the Vitamin D activating enzyme 1α-Hydroxylase (CYP27B1) were found to be associated with shorter overall survival and disease free survival in melanomas." (PMID 28323902, 2017). "Reduced expression of CYP27B1 in primary melanomas was associated with shorter overall survival in one study, while expression of CYP24A1 was higher in naevi and early stage melanomas compared to normal skin, but decreased with melanoma progression in another." (PMID 25970336, 2015). "Previously, we found that decreased expression of VDR and CYP27B1 are associated with progression of melanoma and decreased overall and disease-free survival of melanoma patients, and that novel CYP11A1-derived forms of vitamin D have anti-melanoma activity." (PMID 25334067, 2014). "The loss of CYP27B1 activity led to poorer outcomes in melanoma." (PMID 38672780, 2024). "The relation of CYP27B1 expression to melanoma prognosis is also reflected by shorter overall survival and disease-free survival in patients with reduced CYP27B1." (PMID 38927967, 2024). "CYP27B1 expression decreased with the progression of melanocytic tumors in the following order: nevi—melanoma—melanoma metastases." (PMID 38927967, 2024). "Melanomas at the radial growth phase showed comparable CYP27B1 expression to nevi, and superficial spreading melanomas showed comparable CYP27B1 expression to nodular melanomas." (PMID 38927967, 2024). "Normal skin typically has high levels of CYP27B1 expression (>10%); nevertheless, CYP27B1 enzymatic activity (0–5%) has been noted in aggressive forms of melanoma and non-melanoma skin malignancies, including basal cell carcinoma." (PMID 38672780, 2024). "There was a reverse correlation between melanin content and expression of the VDR and CYP27B1 as well as of RORα and γ in human melanoma samples." (PMID 34692525, 2021). "While CYP24A1 levels were high in nevi and early-stage melanomas in comparison to normal epidermis, its level decreased during melanoma progression similarly to CYP27B1 and VDR." (PMID 34692525, 2021). "The presence of another enzyme belonging to cytochrome P450 superfamily, CYP27B1, and also known as 1-alpha-hydroxylase was found in 96.77% melanoma, 100% melanocytes, and in 70.97% other normal cells of the choroid coat." (PMID 31235702, 2019). "The reduction of CYP27B1 correlates with melanoma phenotype and behaviour indicating a role in the pathogenesis and progression of this cancer." (PMID 26828592, 2016). "Despite this similitude in the evolution of CD70 and CYP27B1 expression during melanoma progression, we have observed that the expression of CD70 and melanin are not correlated in the melanoma cell lines used in this study." (PMID 26828592, 2016). "A similar reverse correlation between CYP27B1 expression and tumor progression and aggressiveness was found in melanomas and ovarian cancer." (PMID 26260259, 2015). "Our previous research showed slightly elevated CYP27B1 levels in nevi and significantly reduced CYP27B1 in more advanced melanomas, lymph node metastases and melanoma cases that developed metastases." (PMID 25501638, 2015). "Similarly to VDR, CYP27B1 expression was also lower in highly pigmented melanomas than in amelanotic or slightly pigmented melanomas." (PMID 38927967, 2024). "Interestingly, the expression of activating vitamin D enzyme CYP27B1 was inversely correlated with melanoma progression and overall and disease-free survival times and such correlation was amplified by a concomitant decrease in the VDR expression." (PMID 34692525, 2021).
melanoma (continued). "Additionally, an inverse correlation has also been documented between the expression of the vitamin D receptor (VDR) and a crucial vitamin D activating enzyme (CYP27B1) with melanoma progression and disease outcome." (PMID 35004285, 2021). "Finally, an inverse correlation between vitamin D receptor, VDR, and 1α-hydroxylase (CYP27B1), the enzyme responsible for the synthesis of the biologically active form of vitamin D, was documented with melanoma progression and disease outcome." (PMID 35004285, 2021). "In addition, the presence of specific polymorphisms of VDR or a decreased expression of VDR, CYP27B1, CYP24A1 and defects in vitamin D signaling are linked to more advanced stages of melanoma or poorer prognosis." (PMID 30200275, 2018). "Since our previous study demonstrated decreased CYP27B1 expression during melanoma progression and its inverse correlation with Ki67 expression and OS time, we decided to analyze its expression in ovarian cancers in correlation with pathomorphological features." (PMID 25501638, 2015). "A similar relationship was found for CYP27B1 expression in melanomas and ovarian cancers." (PMID 26501255, 2015). "Studies examining associations of polymorphisms in genes coding for vitamin D metabolism-related proteins (1α-hydroxylase [CYP27B1], 1,25(OH)2D-24hydroxylase [CYP24A1], vitamin D-binding protein [VDBP]) and cancer risk are scarce, especially with respect to melanoma." (PMID 22576141, 2012). "In our present hospital-based case–control study, we tested eight vitamin D metabolism-related polymorphisms focusing on the VDBP gene (rs1155563 and rs7041) and the genes coding for CYP27B1 and CYP24A1 (rs4646536 and rs927650) for their association with melanoma risk and melanoma prognosis." (PMID 22576141, 2012). "In addition, the expression of the enzyme-activating vitamin D (CYP27B1) was inversely related to melanin in melanoma cells in vivo and melanoma cells cultured in vitro, while the expression of CYP24A1 was lower in non-pigmented melanomas vs. highly melanized ones." (PMID 35359389, 2022). "Additional research investigates vitamin D’s role in cancer prevention, specifically analyzing VDR, CYP27B1, CYP24A1, and ROR expression in the human uveal tract and melanoma." (PMID 40334012, 2025). "CYP27A1 and CYP27B1 are expressed in MeWo, SK-Mel28, SM, SK-Mel-5, SK-Mel-25, IGR, and MelJuso melanoma cell lines; however, the last four cell lines in this list are not responsive to 25(OH)D3 and calcitriol treatment." (PMID 38672780, 2024). "CYP11A1, CYP24A1, CYP27B1, CYP2R1, and CYP3A4 are expressed in WM98 and A375 human melanoma cell lines." (PMID 38672780, 2024). "In our study we confirmed the presence of CYP27B1 and CYP24A1 in the melanoma cells and their connection with the VDR level." (PMID 31235702, 2019). "This is consistent with our previous observation showing the reduction of OS and DFS of patients with a pigmented melanomas at stage 3 and 4, and on expression of several vitamin D related pathways such as VDR, CYP24A1 and CYP27B1 and HIF-1α." (PMID 27542227, 2016). "In melanomas, like for CD70, the expression of 1α-Hydroxylase (CYP27B1), the enzyme responsible for the synthesis of vitamin D, decreases during the progression of the disease." (PMID 26828592, 2016). "Due to the notable reduction in VDR and CYP27B1 expression, researchers believe that the low levels of these proteins promote melanoma development because of the lack of antiproliferative action of vitamin D." (PMID 38672780, 2024). "CYP11A1 is also expressed in normal melanocytes and melanoma cells, so these cells can potentially carry out the CYP11A1-initiated pathways of vitamin D metabolism, with subsequent modification of products by CYP27B1, CYP24A1, or CYP27A1, which are also expressed in melanoma cells." (PMID 38927967, 2024). "Also, there is no clear relationship between SNPs on vitamin D binding protein (VDBP), CYP27B1, and CYP24A1 and melanoma." (PMID 38927967, 2024).
melanoma (continued). "The melanomas with the presence of other aggressive phenotype markers (higher proliferation index, vertical growth phase, Clark levels III–V and Breslow thickness ≥ 2.1 mm, developing the metastases) had lower CYP27B1 expression." (PMID 38927967, 2024). "On the other hand, the expression of VDR and its splicing variants and other vitamin D related genes (RXR, PDIA3, CYP3A4, CYP2R1, CYP27B1, CYP24A1 and CYP11A1) was detected in WM98 and A375 melanomas with the transcript levels being modulated by vitamin D analogs." (PMID 30200275, 2018). "PCR fragments characteristic for VDR, CYP27A1 and CYP27B1 mRNAs were below the level of detectability in SK-MEL-188b melanoma, which did not respond to vitamin D. Only the mRNA of PDIA3 was detected in this line." (PMID 30200275, 2018). "Finally, pigmentation of human melanomas in vivo shows a reverse correlation with the expression of VDR and CYP27B1." (PMID 25811927, 2015). "CYP27A1, CYP27B1, and CYP2R1 are involved in the activation of vitamin D, whereas CYP24A1 and CYP3A4 are responsible for the degradation of the active vitamin D. CYP24A1, the primary catabolic enzyme of calcitriol, is overexpressed in melanoma tissues and cells." (PMID 38672780, 2024). "Thus, the decreases in both CYP27B1 and VDR expression in uveal melanomas could reflect defects in the local vitamin D signaling pattern, which could facilitate melanoma progression and invasion." (PMID 31235702, 2019). "Thus, genes controlling the turnover of vitamin D (CYP27B1, CYP24A1), vitamin A (ALDH1A3, AKR1B10), and cholesterol (CYP7B1), were up-regulated in psoriasis, whereas melanomas showed downregulation of genes regulating turnover of vitamin A (AKR1C3), and cholesterol (CYP39A1)." (PMID 26901218, 2016). "The higher expression of CYP24A1 in strongly pigmented melanomas was a rather unexpected finding since our previous studies have shown a negative correlation between VDR and CYP27B1 expression." (PMID 25334067, 2014). "Finally, the mRNA level of CYP27B1 was not affected by vitamin D analogues and CYP11A1 was elevated in A375 melanoma cells only after treatment with calcipotriol." (PMID 30200275, 2018).
breast carcinoma (23 papers, 2010 to 2026). "In breast cancer cell lines, the CYP27B1 gene showed reversible DNA hypermethylation which caused CYP27B1 silencing." (PMID 33291213, 2020). "However, altered splice variants of CYP27B1 have been detected in breast cancer cells suggesting the possibility that forms of the CYP27B1 enzyme with altered function could be expressed in breast tumors." (PMID 24982636, 2014). "For instance, specific knockout of the Cyp27b1 gene in mammary epithelium contributed to the accelerated growth of mammary tumor probably as a result of decreased local synthesis of calcitriol." (PMID 33172201, 2020). "CYP27B1 is present in some breast cancer cells, to control the autocrine synthesis of 1,25D, but this enzyme is also active in breast cancer microenvironment." (PMID 27187375, 2016). "Instead, we evaluated variants in vitamin D activity and major metabolism (VDR, CYP27B1, and CYP24A1) in relation to breast cancer risk, particularly in relation to self-reported race and estrogen receptor status." (PMID 22480149, 2012). "A possible explanation of how vitamin D might affect breast cancer biology might be the tumor suppressive effects of vitamin D receptor catabolism, as a defect in the vitamin D receptor (e.g., CYP27B1 and CYP24A1 regulation) led to decreased signaling." (PMID 36986179, 2023). "It was reported that breast cancer cells could metastasize to bone tissue more easily when CYP27B1 was knocked-out in mice, which indicated that CYP27B1 could potentially suppress the metastasis of cancer cells." (PMID 36527000, 2022). "However, in breast cancer, CYP27B1 expression is reduced, thus limiting the protection that can be afforded by serum 25(OH)D." (PMID 35743729, 2022). "We further demonstrated that miR-195 also targets genes involved in de novo lipogenesis, it inhibits cell proliferation, migration, and invasion by targeting FASN, HMGCR, ACACA and CYP27B1 thereby potentially opening new avenues for the treatment of breast cancer." (PMID 30932749, 2019). "In addition, evidence shows the impact of CYP27B1 on the development of breast cancer." (PMID 33172201, 2020). "However, clinical data on CYP27B1 expression in breast cancer is inconsistent and less than 2% of breast cancers annotated in The Cancer Genome Atlas datasets exhibit genomic alterations in CYP27B1." (PMID 24982636, 2014). "In a case (n = 928)-control (n = 843) study of breast cancer in AA and EA women, we measured serum 25OHD levels in controls and tested associations between risk and tag single nucleotide polymorphisms (SNPs) in VDR, CYP24A1 and CYP27B1, particularly by ER status." (PMID 22480149, 2012). "Variants in CYP2R1, CYP24A1, CYP27B1, and DBP have been reported to influence circulating 25(OH)D concentrations and provide evidence for a hypothesis that these polymorphisms may be associated with breast cancer risk by altering vitamin D metabolism and signaling." (PMID 42292230, 2026). "For example, miRNA-195 suppressed the proliferation, invasion and metastasis of breast cancer cells via FASN, HMGCR, ACACA and CYP27B1." (PMID 27813492, 2016). "This is similar to reports in human CRC18 and breast cancer, where CYP24A1 overexpression goes hand in hand with higher CYP27B1 levels." (PMID 26238339, 2016). "The role of pro-apoptotic hsa-miR-195 in inhibiting de novo lipogenesis via targeting genes overexpressed in breast cancer (BCL-2, FASN, ACACA, HMGCR, CYP27B1) makes hsa-miR-195 an effective anticancer molecule." (PMID 26632252, 2015). "The functions of CYP27B1 and VDR in prevention of breast cancer are supported by data from animal models." (PMID 24982636, 2014). "Overall, our results on the expression of the VDR, CYP27B1 and CYP24A1 suggest that there is a deregulation of the Vitamin D metabolic and signalling pathways in breast cancer, in order to favour tumour progression." (PMID 20831823, 2010).
breast carcinoma (continued). "A fully characterized series of 189 breast carcinomas in situ arranged in 22 TMAs was assessed for the expression patterns of VDR, CYP27B1 and CYP24A1." (PMID 20831823, 2010). "In summary, this is the first study to report the expression of the VDR, CYP27B1 and CYP24A1 in a series of normal breast, preneoplastic mammary lesions, breast carcinomas in situ and invasive tumours." (PMID 20831823, 2010). "The debated influence of D3 on breast cancer proposes some answers to breast cancer statistics: as both VDR and CYP27B1 upregulate during lactation, it may be the factor contributing to positive influence of breastfeeding on breast cancer incidence." (PMID 34638264, 2021). "Our findings provide evidence that microRNA-195 attenuates epithelial-mesenchymal transition (EMT) in breast cancer cells by targeting FASN, HMGCR, ACACA and CYP27B1 and strongly suggest that overexpression of miR-195 may have therapeutic value in treating breast cancer." (PMID 26632252, 2015). "The levels of protein expression of CYP27B1 and CYP24A1 have not been previously studied in breast cancer." (PMID 20831823, 2010).
rickets (19 papers, 2011 to 2025). Bone softening and weakening usually caused by deficiency or impaired metabolism of vitamin D. Deficiency of calcium, magnesium, or phosphorus may also cause rickets. "The GG genotype of rs10877012 CYP27B1 was significantly associated with susceptibility of having hypovitaminosis D, whereas the CT genotypes of rs731236 TaqI VDR confer susceptibility to RA and high clinical disease activity in the Mexican mestizo population." (PMID 40870018, 2025). "Deficiency of the 1α-hydroxylation of 25OHD by biallelic silencing mutations of CYP27B1 is known as pseudodeficiency rickets, vitamin D dependency rickets, or OMIM #264700." (PMID 35334824, 2022). "We have also developed an in vivo system including a Cyp27b1-gene-deficient rat (a type I rickets model), a Vdr-gene-deficient rat (a type II rickets model), and a rat with a mutant Vdr (R270L) (another type II rickets model) using a genome editing method." (PMID 34769269, 2021). "For Cyp27b1-gene-deficient and Vdr mutant (R270L) rats, amelioration of rickets symptoms can be used as an index of the efficacy of vitamin D derivatives." (PMID 34769269, 2021). "In contrast, vitamin D-dependent rickets type 1 arises from CYP27B1 loss-of-function mutations that abolish 1α-hydroxylase activity, leading to deficient 1,25-dihydroxyvitamin D3 production, hypocalcemia, secondary hyperparathyroidism, and rickets." (PMID 41155848, 2025). "Notably, carriers of the GG genotype of rs10877012 (CYP27B1) have an increased susceptibility to hypovitaminosis D, reinforcing the gene’s role in regulating serum calcidiol levels." (PMID 40870018, 2025). "Specifically, carrying the GG or TT genotype for the rs10877012 variant in CYP27B1 confers a 1.7-fold increased susceptibility to hypovitaminosis D (OR = 1.7; CI = 1.1–2.7; TA = 0.57; CVC = 10/10; p = 0.02) compared with carriers of the GT genotype or being a carrier of any other SNVs analyzed." (PMID 40870018, 2025). "Logistic regression confirmed that the GG genotype of rs10877012 (CYP27B1) was associated with hypovitaminosis D (OR = 1.8; CI: 1.1–3.0; p = 0.01), and the CT genotype of rs731236 TaqI (VDR) with RA (OR = 1.9; CI: 1.2–2.9; p < 0.01) and high DAS28-ESR (OR = 3.6; CI: 1.3–10.7; p < 0.01)." (PMID 40870018, 2025). "Two other recessively inherited forms of rickets in humans are due to the disruptions of either the synthesis or metabolism of vitamin D. Vitamin D-dependent rickets type I (VDDR-I) is caused by mutations in the CYP27B1 gene, which encodes vitamin D 1-alpha-hydroxylase." (PMID 21747952, 2011). "In CYP27B1-related rickets, genotype–phenotype correlations inform disease severity and therapeutic requirements; for instance, the c.195+2T>G splice-site variant has been linked to more severe phenotypes and higher calcitriol needs." (PMID 41155848, 2025). "In humans with inactive VDRs, and in Vdr null and Cyp27b1 null neonatal mice, a diet enriched in calcium, or parenteral use of calcium, maintains normal mineral metabolism and prevents rickets." (PMID 38477809, 2024). "In patients with rickets, initial hypophosphatemia, normocalcemia, and normal 25(OH)D3, CYP27B1 should be investigated as a possible diagnosis." (PMID 39452491, 2024). "Seven of the amelogenesis imperfecta-associated genes (CYP27B1, EPNN1, PHEX, SLC4A1, SLC4A4, VDR, and WDR72) are known to cause rickets when mutated." (PMID 33672174, 2021). "Although Cyp27b1-knockout (KO), Vdr-KO, and Vdr (R270L) rats each showed rickets symptoms, including abnormal bone formation, they were significantly different from each other." (PMID 32231239, 2020). "Marked cartilaginous disorganization was seen in the growth plates of Cyp27b1-KO rats, Vdr (R270L) rats and Vdr-KO rats at 15 weeks of age, as evidenced by toluidine blue staining, indicating the histological features of rickets." (PMID 32231239, 2020).